U6 (U6 spliceosomal RNA )
Gene: Small nuclear RNA gene on chromosome 11 (87,648,489 to 87,648,549, reverse strand). Ensembl gene ENSG00000283412.
Homologues: Orthologues: mouse Gm26122 (77% identical), rat LOC120094865 (64% identical). Paralogues in human: RNU6-144P (84% identical), RNU6-16P (84% identical), RNU6-46P (84% identical), RNU6-959P (84% identical), RNU6-1 (82% identical), RNU6-1060P (82% identical), RNU6-10P (82% identical), RNU6-1263P (82% identical), RNU6-1323P (82% identical), RNU6-15P (82% identical), RNU6-2 (82% identical), RNU6-20P (82% identical), and 1285 more.